STAT3 (signal transducer and activator of transcription 3)
Diseases named in the same sentence as STAT3 in open-access papers (continued):
Sharing a sentence is not in itself a finding about the gene and the disease.
tumor (continued). "Thus, collectively, IL-6/JAK/STAT3 pathway contributes to the development of a highly immunosuppressive tumor microenvironment." (PMID 32824865, 2020). "Thus, uSTAT3 possesses noncanonical function in promoting heterochromatin formation, and the tumor suppressor function of STAT3 is likely attributable to the heterochromatin-promoting activity of uSTAT3 in the non-canonical JAK/STAT pathway." (PMID 32087696, 2020). "Anti-tumor compounds are able to target STAT3 in GC therapy." (PMID 32545648, 2020). "In addition, the use of NF-κB or STAT3 inhibitor decreased PD-L1 expression in adi-CM-treated tumor cells, which provided more evidence that TNF-α and/or IL-6 signaling mediated the regulation of PD-L1 in adi-CM-treated tumor cells." (PMID 32477009, 2020). "In addition, Trichomicin inhibited TNFα-induced activation of NF-κB and basal Stat3 signaling in vitro, which resulted in reduced expression of the immune checkpoint protein PD-L1 in tumor and stromal cells." (PMID 32317968, 2020). "Our results up to this point indicated that STAT3 inhibition could impair tumor growth, increase tumor T lymphocyte infiltration, and decrease tumor systemic effects." (PMID 33330068, 2020). "Particularly it was seen to play a key role in the apoptotic signaling of the tumor cell through direct stimulation of caspases cascade and the inhibition of the anti-apoptotic pathways such as PTEN/PI3K/AKT, Sirt-1, AMPK/YAP, NF-κB and STAT3 that contribute to tumor cell immortality." (PMID 32331450, 2020). "Moreover, the crosstalk between PTEN and STAT3 provides new insight into the tumor development mechanism, which has great significance for the exploration of HNSCC progression and new therapeutic targets." (PMID 32471980, 2020). "STAT3 is an important signaling pathway in tumor development." (PMID 33330466, 2020). "A variety of inhibitors of Jak kinases or Stat3 have entered clinical trials for cancer treatment, owing primary to the multifaceted functions of the Jak/Stat3 pathway in facilitating cancer cell proliferation, survival and metastasis, tumor angiogenesis and immunosuppression." (PMID 33679721, 2020). "The impact of β-caryophyllene oxide on STAT3 activation, related protein kinases and phosphatases, STAT3-directed gene products, and apoptosis was investigated utilizing both functional proteomics and different tumor cell lines." (PMID 32545187, 2020). "Phenotypically, peptide-induced STAT3 inhibition decreased colony formation and reduced xenograft tumour growth, confirming that peptide inhibition of the Rac1–STAT3 axis could be of therapeutic utility." (PMID 32915198, 2020). "Indeed, STAT3 is also frequently activated in a variety of human cancer cells, STAT3 signaling transduction promotes the growth and survival of tumor cells." (PMID 33224886, 2020). "This might provide some clues for the role of STAT3/survivin pathway in the radioresistance of various neoplasms." (PMID 32733808, 2020). "Consistent with our findings, it has been shown that IL-10R signaling is involved in overstimulation of STAT3, enabling tumor cells to grow uncontrollably and to become resistant to the induction of apoptosis, confirming the link demonstrated here between IL-10 and STAT3." (PMID 32222879, 2020). "Moreover, in vivo assays with osthole confirmed the suppression of STAT3 phosphorylation as well as reduction of tumor growth in TNBC xenograft mice." (PMID 33138097, 2020). "Thus, targeted inhibition of the S1PR1/STAT3 can inhibit tumor proliferation and growth in a STAT3-dependent manner." (PMID 33101013, 2020). "Hence, turmeric can efficiently obstruct the proliferation of tumor cells by the suppression of NF-κB and STAT3 pathways." (PMID 32454872, 2020). "Overall, the results support the notion that targeting the STAT3 pathway through drugs such as atovaquone and pyrimethamine not only inhibits tumor growth but may also decrease the immunosuppressive microenvironment in MPM." (PMID 33374980, 2020).
tumor (continued). "Collectively, the activation of NF-κB and STAT3 signaling transduction pathways in cancer cells, as well as in the inflammatory cells in the tumor microenvironment, provide a great advantage for tumor cell proliferation, survival, migration, and immune evasion." (PMID 33143283, 2020). "The anti-tumor compounds inhibit EMT via STAT3 downregulation." (PMID 32545648, 2020). "Notably, CCL5 signaling activates the NF-κB and STAT3 signal pathways, then facilitating tumor angiogenesis." (PMID 31949487, 2020). "STAT3 promotes inter-cellular interactions in the tumor microenvironment." (PMID 33679700, 2020). "Further molecular analysis of residual orthotopic and heterotopic tumor tissues treated with the drug revealed decreased Ki67 levels and STAT3 signaling, as well as a decrease in MES phenotypes, which reveals the therapeutic potential of pioglitazone in vitro and in vivo." (PMID 32280134, 2020). "Based on the results of the present studies, STAT3 may play a relatively important role in tumor and inflammatory biology, while STAT4 appears to be less involved." (PMID 33505963, 2020). "Moreover, we found that STAT3 overexpression reversed the tumor-suppressing ability of si-circ_0006916." (PMID 33292166, 2020). "The reason why we add a JNK inhibitor is because JNK signaling is also related to STAT3 activity, and is to confirm that the JAK2/STAT3 signaling pathway uniquely plays an important role in maintaining self-renewal and tumor initiating capacity of CSCs, and enhancing stemness characters." (PMID 32326231, 2020). "Immunoblotting analyses of three tissues as random in each group showed that eEF2K depletion increased STAT3 phosphorylation and c-Myc expression in tumor tissues, supporting that eEF2K regulates STAT3 phosphorylation and c-Myc expression and subsequent tumor growth." (PMID 32054489, 2020). "This study also noted that several gp130 cytokines (IL-6, LIF, CT-1, and CNTF) were able to significantly increase the CSC population in HMECs, pointing to their potential role as microenvironmental cytokines capable of promoting tumor progression through STAT3." (PMID 32023849, 2020). "Hence, with the presence and activation of STAT3, we can infer that it holds a negative regulatory role in releasing cytokines that draw affinity towards tumor infiltration." (PMID 33291616, 2020). "Moreover, myeloid-restricted Stat3 deletion leads to enhanced production of IL-12 and reduced expression of tumor-promoting cytokines such as IL-23 and IL-10." (PMID 31947933, 2020). "Moreover, TNF-α, IL-6, and several typical differentially expressed phosphorylated proteins (such as p-CCNB1, p-FOXO3, and p-STAT3) in tumor tissues, tumor cell viability, and cell cycle arrest assay in vitro further verify the results of IPA." (PMID 33344655, 2020). "In the TME, persistent STAT3 activation has been shown to suppress the M1 phenotype and promote anti-inflammatory M2 polarization of TAMs, which further promotes tumor growth by enhancing angiogenesis, immunosuppression, cancer cell invasion, and metastasis of several cancer models." (PMID 33335857, 2020). "The STAT3 signaling pathway is essential during physiological and tumor angiogenesis." (PMID 33614496, 2020). "Interestingly, while LIF is known to activate the same downstream signaling pathways as OSM and IL-6, STAT3 appears to play a contradictory role in the context of tumor cell dormancy in the bone." (PMID 32023849, 2020). "Nevertheless, the findings from this experiment indicated a decrease in p-STAT3 after siltuximab treatment, and the researchers speculated that siltuximab had no clinical effect possibly because of tumour autocrine IL-6 and tumour heterogeneity." (PMID 32760201, 2020). "BCL-2 is a factor that promotes tumor cell proliferation and inhibits tumor cell apoptosis and may be a downstream target gene for the STAT3 signaling pathway." (PMID 33746736, 2020).
tumor (continued). "Although there are some studies showing that STAT3 may be a tumor suppressor, STAT3 has been identified as an oncogene contributing progression in cancer." (PMID 32486001, 2020). "Moreover, to determine the effects of polyphenol treatment on tumor growth and on another chemosensitization factor, we analyzed the level of STAT-3 phosphorylation (pSTAT-3)." (PMID 31974389, 2020). "A great many of clinical data also demonstrate that overexpressed and/or constitutively activated STAT3 is frequently observed in tumor cells as well as tissue samples, and contributes to tumorigenesis and progression in the majority of cancers, including HCC6,7." (PMID 31980595, 2020). "Furthermore, the increased phosphorylation of S727 correlates with mitochondrial STAT3 metabolic activity in tumours, whereas the prominence of Y705 favours aerobic glycolysis." (PMID 32731620, 2020). "STAT3 is phosphorylated in 60% of human HCC and active STAT3 correlates with tumor aggressiveness." (PMID 32328178, 2020). "Here, STAT3 regulates NF-κB-dependent expression of tumor cell derived Chemokine (C-X-C motif) ligand 1 (the mouse orthologue to human IL-8) by sequestering NF-κB in the cytoplasm, thereby impairing pro-tumorigenic myeloid tumor infiltration and tumor vascularization." (PMID 32365499, 2020). "Our findings indicate that the T cell infiltration in the tumor microenvironment may be improved by inhibiting STAT3 signaling." (PMID 32503584, 2020). "Moreover, MLN8237 upregulates inhibition the AURKA protein level, activates the Akt/Stat3 pathway, and increases the antiapoptosis activity of tumor-initiating cells." (PMID 31920463, 2020). "Within a tumour cell, it exhibits an overly expressed STAT3 pathway." (PMID 32863742, 2020). "However, several promising potential therapy targets exist in the form of using neutralizing antibodies, JAK2/STAT3 pathway-specific inhibitors, and silencing the expression of pre-cancerous interleukins secreted by CAFs in the tumor microenvironment." (PMID 32268527, 2020). "While a systemically stable cyclic STAT3 decoy has been shown to have an anti-cancer effect after intravenous injection, the opportunity to increase concentrations of the STAT3 decoy to the tumor region using targeted delivery approaches remains relatively unexplored." (PMID 33206698, 2020). "Moreover, NF-κB and STAT3 can physically interact and cooperate in regulating the interaction of malignant cells and the tumor microenvironment, especially immune cells, such as TAMs." (PMID 32222879, 2020). "CHOP-deficient MDSCs displayed reduced signaling through C/EBPβ, leading to a decreased production of IL-6, and a low expression of phospho-STAT3, whereas the IL-6 expression was sufficient to rescue the immunosuppressive functions of CHOP-deficient MDSCs and restore tumor growth." (PMID 32560326, 2020). "The roles of STAT3 protein include promotion of cell proliferation, cell survival, inflammation, cellular transformation, metastasis of cancer, blood vessel formation and tumour-promoting inflammation." (PMID 32863742, 2020). "STAT3 deletion is also known to reduce tumor growth and prolongs survival in mouse models." (PMID 33081347, 2020). "STAT3 is also known to impact the tumor immune response and cancer stem cells." (PMID 32850390, 2020). "Notably, C188-9 a small STAT3 inhibitor, has been shown to achieve tumor regression in mice with xenografts of radioresistant HNSCC lines." (PMID 33203092, 2020). "In addition to direct effects on tumor cells, IL-6/JAK/STAT3 signaling has a fundamental effect on tumor-infiltrating immune cells." (PMID 32824865, 2020). "In addition, it has been shown that tissue-specific loss of STAT3 or STAT5 in mice promotes cancer growth in certain tissues, and thus these STAT proteins can act as tumor suppressors." (PMID 32087696, 2020). "Whether TLR4 expression is positively correlated with STAT3 activation in tumor-infiltrating immune cells is a question to be addressed." (PMID 32312954, 2020).
tumor (continued). "Our results indicated that M2-polarized macrophages induced by ICC promote tumor growth and invasiveness through IL-10/STAT3-induced EMT and might be a potential therapeutic target for ICC." (PMID 33372604, 2020). "Added to that, in our experimental tumor model, the inhibition of STAT3 increased p65-NFκB expression in TC-1 tumors, which could be a direct or indirect mechanism." (PMID 33330068, 2020). "Moreover, EHD slowed the growth of xenograft tumours in nude mice; decreased the expression levels of STAT3, p-STAT3, and cyclin D1; and upregulated the expression level of P27." (PMID 32382281, 2020). "Finally, the in-vivo assay was conducted and the results revealed that circ-STAT3 promoted HB tumor growth via up-regulating STAT3 and Gli2." (PMID 32493490, 2020). "Taken together, we assume that there might be a feedback loop between ALDH1A3 and STAT3 to promote tumor progression in cancers." (PMID 32680476, 2020). "Notably, numerous reports have demonstrated that STAT3 is involved not only in tumor metastasis but also in proliferation, the cell cycle and apoptosis." (PMID 32358527, 2020). "Additionally, immunochemical analysis showed that p-STAT3 expression was evidently decreased in the tumor tissues of the GNAS-cas9 group, compared to that in the WT group." (PMID 32123532, 2020). "These assays indicated that the effect of Faecalibacterium prausnitzii on JAK2/STAT3 was mediated at least in part by IL-6 and the anti-tumor effect of Faecalibacterium prausnitzii may be through inhibition of the IL6/STAT3 pathway." (PMID 32272885, 2020). "Also, stroma-derived CCL2/CCL5 induces IL-6 release from the tumor cell generating carboplatin resistance through PYK2 pathway activation (positioned upstream of the JAK1/STAT3 pathway), a critical mediator of survival pathway activation." (PMID 32499779, 2020). "Moreover, accumulating evidence reveals that STAT3 hyperactivation can mediate tumor-induced immunosuppression at many levels." (PMID 32972405, 2020). "It is possible that high expression of TIMP-2 in tumours is a pre-requisite for constitutive activation of STAT3 in many cancers or vice versa, constitutive activation of STAT3 may sustain enhanced TIMP-2 expression in certain cancers." (PMID 33023532, 2020). "Not surprisingly, the abrogation of STAT3-associated signaling pathways inhibits M2 polarization and restrains tumor growth." (PMID 33584695, 2020). "STAT3 is also well-known to induce immunosuppression to promote tumor progression." (PMID 33335857, 2020). "The secretion of Il-6 and Il-8 by GC-derived mesenchymal stromal cells and further activation of the JAK2/STAT3 pathway induces the polarization of macrophages into pro-tumor M2 phenotype, which consequently promotes GC metastasis via advancing the EMT process." (PMID 32268527, 2020). "In addition, the expression of Stat3 was reduced in the tumor with MNX1-AS1 knockdown and the lung metastasis was found in the control group (2 out of 5) but not in the MNX1-AS1 silencing group." (PMID 32754442, 2020). "Taken together, STAT3 might correlate with M2 macrophage, Tregs, and T-cell exhaustion, regulating immune suppression in the tumor microenvironment." (PMID 32486001, 2020). "Moreover, miR-125b-5p displayed a tumor suppressive role in the cells with hyperactivated mTORC1 via targeting signal transducer and activator of transcription 3 (STAT3)." (PMID 31949495, 2020). "Importantly, we found that inhibition of ERK or STAT3 resulted in significantly impaired cytotoxicity against tumor cells." (PMID 33123602, 2020). "To examine whether STAT3 regulates the anti-tumor activity of CD103+ cDC1s, we used an established intratumoral (i.t.)vaccination strategy." (PMID 31947933, 2020).
tumor (continued). "MiR-142-3p could limit the generation of MDSCs during tumor-induced myelopoiesis by modulating STAT3 and CCAAT/enhancer-binding protein β (C/EBPβ) signal pathways." (PMID 33613512, 2020). "Thus, targeting constitutive STAT-3 signaling is aremarkable therapeutic methodology for tumor progression." (PMID 32167126, 2020). "We investigated whether A009 extracts could act on STAT3 pathway, a major hub in the onset of tumor progression." (PMID 32224910, 2020). "Such tumor-promoting effects were regulated through JAK/STAT3 pathways." (PMID 33057049, 2020). "Overactivation of the Jak2/STAT3 signaling pathway induced by tumor-derived factors may be responsible for irregular DC differentiation and function in colon cancer." (PMID 32656079, 2020). "Notably, STAT3 signaling in tumor cell is a key signaling mechanism activated by cytokines and growth factor receptors that establish an immunosuppressive microenvironment during the early stages of breast carcinogenesis to promote tumor growth and metastases." (PMID 32751846, 2020). "Constitutive activation of STAT3 in many tumors is important for tumor growth and progression." (PMID 32264893, 2020). "However, intratumoral injection of sialidase in mice alone activates STAT3 in tumor myeloid cells and increased the infiltration of myeloid cells, accelerating the tumor growth." (PMID 33224886, 2020). "Considering the association between STAT3 and EMT, their interplay in CSCs, and the in vitro effects of bazedoxifene, we suggest that this compound could act as an inhibitor of tumor-initiating cells, although this hypothesis must be further investigated." (PMID 33138097, 2020). "Various factors in a tumor could induce the expansion or activation of MDSCs through multiple pathways, including STAT3 or IL-4Rα–STAT6 pathways, resulting in the suppression of T-cell function." (PMID 32983146, 2020). "STAT3 is activated in myeloid cells and promote tumor immunosuppression." (PMID 32983125, 2020). "This pro-differentiating role for STAT3 contradicts previous work describing its role in promoting CSCs traits among different cancer types, thus highlighting the importance of the tumor context." (PMID 32296435, 2020). "Positive CD30 tumor phenotype was associated with higher STAT3 and AKT phosphorylation, but not with pMAPK." (PMID 32188095, 2020). "Furthermore, it has been reported that STAT3 inhibition in the myeloid compartment remarkably induces the anti-tumor capabilities of T cells and promotes their expansion in vivo." (PMID 32150944, 2020). "Notably, the components of the tumor microenvironment that are capable of targeting STAT3 in GC, such as fibroblasts and macrophages, are discussed in this review." (PMID 32545648, 2020). "The anti-tumor compounds can target the STAT3 signaling pathway in cancer therapy." (PMID 32545648, 2020). "In further pre-clinical studies, co-treatment of cells with paclitaxel and a JAK2 inhibitor, NVP-BSK805, could significantly reduce STAT3 phosphorylation, and in vivo tumor growth, when compared with paclitaxel alone." (PMID 32328465, 2020). "Interestingly, co-culturing C2C12 cells with HCT116 tumor cells led to drastic myotube atrophy (−53%, P<0.0001), accompanied by markedly increased phosphorylation of STAT3 (+149%, P<0.0001)." (PMID 31915140, 2020). "Additionally, IL6/JAK/STAT3 signaling pathway has been proposed as one of the mechanisms that can affect tumor microenvironment and immune response to tumor cells." (PMID 33080912, 2020). "Mechanistically, tumor lysates stimulated SOCS3 knockout macrophages in vitro, their STAT3 phosphorylation is enhanced and TNF-α and IL-6 are reduced, and higher levels of MCP2/CCL8 via STAT3 are produced to combat tumor metastasis in contrast to normal macrophages." (PMID 33224886, 2020).